TRAP1 (TNF receptor associated protein 1)
Description:
Chaperone that expresses an ATPase activity. Involved in maintaining mitochondrial function and polarization, downstream of PINK1 and mitochondrial complex I. Is a negative regulator of mitochondrial respiration able to modulate the balance between oxidative phosphorylation and aerobic glycolysis. The impact of TRAP1 on mitochondrial respiration is probably mediated by modulation of mitochondrial SRC and inhibition of SDHA.
Synonyms: HSP 75; TRAP-1; HSP75; HSP90L
Tractability: Small molecule: a structure with a bound ligand is known; a high-quality ligand is known; it belongs to a druggable protein family. PROTAC: ubiquitination databases record sites on it; its protein half-life has been measured; a small molecule that binds it is known.
Target class: Other cytosolic protein
Gene: Protein-coding gene on chromosome 16 (3,651,639 to 3,717,591, reverse strand). Ensembl gene ENSG00000126602.
Subcellular location: Mitochondrion; Mitochondrion inner membrane; Mitochondrion matrix
Subcellular location (Human Protein Atlas): Mitochondria
Pathways (Reactome):
Metabolism: Citric acid cycle (TCA cycle); Respiratory electron transport
Gene Ontology:
Molecular function: ATP hydrolysis activity; protein binding; protein kinase binding; ATP binding; tumor necrosis factor receptor binding; ATP-dependent protein folding chaperone
Biological process: negative regulation of cellular respiration; translational attenuation; negative regulation of intrinsic apoptotic signaling pathway in response to hydrogen peroxide; negative regulation of reactive oxygen species biosynthetic process; protein folding
Cellular component: membrane; mitochondrial inner membrane; mitochondrial matrix; mitochondrion; mitochondrial intermembrane space; intracellular organelle lumen
Genetic constraint (gnomAD): Loss-of-function variants: 103 observed, 90.35 expected, observed/expected ratio (o/e) 1.14, 90% interval 0.97 to 1.34. The synonymous counts are far from expectation, so gnomAD's model fits this gene poorly and the ratio says little. Missense variants: 1,229 observed, 944.24 expected, observed/expected ratio (o/e) 1.3, 90% interval 1.24 to 1.36. Synonymous variants: 498 observed, 378.28 expected, observed/expected ratio (o/e) 1.32, 90% interval 1.22 to 1.42.
Homologues: Orthologues: chimpanzee TRAP1 (99% identical), macaque TRAP1 (96% identical), guinea pig TRAP1 (89% identical), rat Trap1 (88% identical), mouse Trap1 (88% identical), dog TRAP1 (86% identical), pig TRAP1 (86% identical), tropical clawed frog trap1 (78% identical), zebrafish trap1 (75% identical), Drosophila melanogaster Trap1 (50% identical), Caenorhabditis elegans hsp-75 (42% identical). Paralogues in human: HSP90AA1 (32% identical), HSP90AB1 (31% identical), HSP90B1 (31% identical).
Diseases named in the same sentence as TRAP1 in open-access papers:
TRAP1 is named in the same sentence as 123 diseases in open-access papers, as found by Europe PMC text mining. Sharing a sentence is not in itself a finding about the gene and the disease. The quoted sentences say what the papers report.
colorectal carcinoma (28 papers, 2011 to 2024). A malignant epithelial neoplasm that arises from the colon or rectum and invades through the muscularis mucosa into the submucosa. "Recent studies show that TRAP1 is associated with positive lymph node metastasis, multi-drug resistance, and shorter median overall survival in colorectal cancer." (PMID 28088229, 2017). "The novel marker tumor necrosis factor receptor-associated protein 1 (TRAP1) is a mitochondrial heat shock protein that has been related to drug resistance and protection from apoptosis in colorectal cancer." (PMID 28088229, 2017). "Recent reports revealed aberrant up-regulation of TRAP1 in pancreas, colon, lung, prostate and colorectal cancers, whereas significant loss of TRAP1 expression was also observed in non-Hodgkin lymphomas and pancreatic neuroendocrine tumors." (PMID 26517089, 2015). "TRAP1 is up-regulated in ulcerative colitis associated colorectal cancer." (PMID 38098505, 2023). "Tumor Necrosis Factor Receptor-Associated Protein 1 (TRAP1) is a heat shock protein 90 (HSP90) molecular chaperone overexpressed in 60–70% human colorectal carcinomas (CRCs) and the co-upregulation of TRAP1 and associated 6-related proteins identifies metastatic CRCs with poor prognosis." (PMID 31878280, 2019). "Moreover, TRAP1 silencing in HCT116 colorectal cancer cells resulted in the loss of the stem-like signature." (PMID 29621137, 2018). "In addition, it is known that TRAP1 expression is significantly associated with lymph node metastasis in colorectal cancers, prostatic cancers, and esophageal squamous cell carcinomas." (PMID 28088229, 2017). "TRAP1 also cooperate with soluble resistance-related calcium-binding protein (sorcin) in human colorectal carcinoma in a survival pathway, which is responsible for inducing multi-drug resistance." (PMID 38098505, 2023). "Condelli report that TRAP1 can participate in the progression of colorectal cancer through regulating the synthesis and ubiquitination of BRAF." (PMID 38098505, 2023). "In human colorectal cancer cells and tissues, with high TRAP1 background, the protein expression and phosphorylation of p70S6K is reduced." (PMID 38098505, 2023). "TRAP1 has been suggested as a predictive marker for prognosis in colorectal cancer, human metastatic colorectal carcinoma and ulcerative colitis-associated colorectal cancer." (PMID 38098505, 2023). "In agreement with our findings, it was shown that TRAP1 is a determinant of metabolic rewiring in colorectal cancer and favors resistance to the EGFR inhibitor, cetuximab." (PMID 37508418, 2023). "When colorectal cancer is under oxygen deprivation, TRAP1 regulates the response of cells to hypoxia and inhibits ribosome biogenesis." (PMID 38098505, 2023). "For example, low expression of TRAP1 correlated with high-grade cervical and bladder cancer, while high TRAP1 expression was found in colorectal carcinomas." (PMID 35127545, 2022). "Conversely, TRAP1 has been well-characterized to facilitate disease progression and induce drug resistance in colorectal cancer, where it enhances glycolysis." (PMID 36510251, 2022). "In colorectal cancer and its animal models, increased TRAP1 expression was found to be localized to pro-neoplastic lesions in the tumor." (PMID 35883436, 2022). "The HSP90 molecular chaperone TRAP1 is upregulated in 60–70% of human colorectal carcinomas (CRCs) and favors stem cells maintenance, modulating the Wnt/β-Catenin pathway and preventing β-Catenin phosphorylation/degradation." (PMID 33065966, 2020). "TRAP1 is an HSP90 molecular chaperone upregulated in human colorectal carcinomas (CRCs) and responsible for downregulation of oxidative phosphorylation (OXPHOS) and adaptation to metabolic stress." (PMID 33025742, 2020).
colorectal carcinoma (continued). "TRAP1 overexpression prevents HT-29 colorectal cancer cells from undergoing apoptosis induced by 5-fluorouracil, oxaliplatin, and irinotecan, while shepherdin overcomes the resistance to these chemotherapeutic drugs by inhibiting the TRAP1 ATPase." (PMID 33575209, 2020). "In this study, the mechanism of TRAP1 modulation in colorectal carcinoma was addressed in in vivo and in vitro models." (PMID 31878280, 2019). "Early evaluation of TRAP1 expression in a limited number of human colorectal carcinomas showed up-regulation compared with normal matched peritumoral mucosa in 65% of cases." (PMID 29621137, 2018). "Accordingly, immunohistochemistry analyses of 714 cases of colorectal carcinoma have shown that high TRAP1 expression was observed in 79% of cases." (PMID 29621137, 2018). "We further visualized TRAP1/SDOS interaction by in situ proximity ligation assay (PLA) in HCT116 colorectal carcinoma cells." (PMID 30260431, 2018). "Accordingly, a protein signature predictive of poor prognoses in advanced disease was identified by proteomic analysis of the TRAP1 protein network in human colorectal carcinomas." (PMID 29621137, 2018). "Accordingly, TRAP1 levels increased in colorectal carcinoma cells resistant to 5-fluorouracil, oxaliplatin and irinotecan and, in turn, its overexpression led to drug-resistance." (PMID 29621137, 2018). "TRAP1 expression is enhanced in stem cells located at the bottom of intestinal crypts and in cancer stem cells separated from colorectal cancer cell lines." (PMID 29621137, 2018). "TRAP1 expression significantly increased in colorectal cancer at the advanced pathological stage, being significantly correlated with poor survival rates, although only marginally associated with lymph node involvement and tumor differentiation." (PMID 29621137, 2018). "TRAP1 phosphorylation by BRAF, the first Ser/Thr kinase activated downstream to Ras, was associated with resistance to apoptosis in colorectal carcinoma models." (PMID 28405578, 2017). "It has been recently demonstrated that TRAP1 is responsible for a multi-drug resistant phenotype in human colorectal carcinoma cells." (PMID 28088229, 2017). "TRAP1 is upregulated at the transition between low- and high-grade adenomas, in in situ carcinomas and in about 60% of human colorectal carcinomas, being downregulated only in a small cohort of tumors." (PMID 28177905, 2017). "TRAP1 expression levels were also increased in cisplatin-resistant ovarian carcinoma cell lines, colorectal carcinoma cells resistant to 5-fluorouracil, oxaliplatin and irinotecan, and breast carcinoma cells resistant to paclitaxel." (PMID 28088229, 2017). "But TRAP1 seems to be one of the critical players in biologic processes of tumor invasion in colorectal cancer." (PMID 28088229, 2017). "This information confers that TRAP1 expression is not only a prognostic factor but also a predictive factor for colorectal cancer." (PMID 28088229, 2017). "Despite these findings, investigations at a large scale from human colorectal tissues have been limited to evaluate the relationships between TRAP1 expression and colorectal cancers with various clinicopathologic parameters." (PMID 28088229, 2017). "But there are still limited researches about relationship between TRAP1 expression and pathologic parameters in colorectal cancers." (PMID 28088229, 2017). "Recently, several investigations have shown that TRAP1 is a significant factor related to metastasis and prognosis in colorectal cancers." (PMID 28088229, 2017). "TRAP1 expression was significantly increased in colorectal cancer with advanced pathologic T-stage compared with that in early T-stage (p = 0.008)." (PMID 28088229, 2017). "This study aims to delineate the clinicopathologic significance of TRAP1 expression in colorectal cancer." (PMID 28088229, 2017).
colorectal carcinoma (continued). "Until now, only a limited number of studies have delineated the pathophysiologic functions of TRAP1 and relationships between TRAP1 and clinicopathologic factors including histology in human colorectal cancer tissue." (PMID 28088229, 2017). "Several groups have suggested TRAP1 as a predictive marker for prognosis in colorectal cancer, ovarian cancer, esophageal squamous cell cancer, non-small cell lung cancer, and ulcerative colitis-associated colorectal cancer." (PMID 26517089, 2015). "TRAP1 levels are markedly elevated in HT-29 colorectal carcinoma cells resistant to 5-fluorouracil, oxaliplatin and irinotecan; while TRAP1 overexpression can recreate this MDR phenotype in a number of different neoplastic cell types." (PMID 27721330, 2011). "TRAP1 regulates stemness through Wnt/β-catenin pathway in human colorectal carcinoma." (PMID 38098505, 2023). "TRAP1 is possibly involved in the regulation of colorectal cancer through a variety of mechanisms." (PMID 38098505, 2023). "TRAP1 expression is higher in tumour tissues compared to surrounding non-malignant tissues, and elevation of TRAP1 protein levels and gene copy number correlate with malignant progression and metastasis of colorectal carcinoma." (PMID 34769108, 2021). "Moreover, results of in vitro and in vivo studies of TRAP1 in human breast and colorectal carcinoma indicated that TRAP1 is involved in the mechanism regulating the synthesis/ubiquitination of BRAF but does not influence its stability." (PMID 33575209, 2020). "Notably, TRAP1 regulated the phosphorylation and degradation of βCatenin, thus positively controlling the Wnt/βCatenin pathway, which is activated in colorectal cancers with high TRAP1 expression." (PMID 29621137, 2018). "TRAP1 is a HSP90 molecular chaperone upregulated in colorectal carcinomas and involved in control of intracellular signaling, cell cycle, apoptosis and drug resistance, stemness and bioenergetics through co-traslational regulation of a network of client proteins." (PMID 28177905, 2017). "TRAP1 and/or its client proteins were quantified, by immunoblot analysis, in 60 surgical specimens of colorectal carcinomas at different stages and, by immunohistochemistry, in 9 colorectal adenomatous polyps, 11 in situ carcinomas and 55 metastatic colorectal tumors." (PMID 28177905, 2017). "As TRAP1’s full name, tumor necrosis factor receptor-associated protein 1 implies, TNF-α promotes tumor invasion via induction of matrix metalloproteinases, and finally modulates EMT in a model of colorectal cancer." (PMID 28088229, 2017). "Consequently, our data demonstrated that TRAP1 expression was a good prognostic biomarker for depth of invasion and disease-specific survival in colorectal cancer." (PMID 28088229, 2017). "In this study, we delineate clinicopathologic significance of TRAP1 using a large number of formalin-fixed paraffin-embedded (FFPE) specimens of colorectal cancers to investigate its potential as a biomarker, and analyze the prognostic significance of the TRAP1 status." (PMID 28088229, 2017). "Here, we found that overexpression of TRAP1 might contribute to tumor cell local invasion of colorectal cancer." (PMID 28088229, 2017). "Further studies on TRAP1 expression with clinical trial might contribute to building a new era of personalized medicine in treatment for colorectal cancer." (PMID 28088229, 2017). "Notably, AKT and p70S6K undergo translational regulation by TRAP1 in colorectal cancers 15, 16 and such regulation affects cell migration in HEK293 cells, in which TRAP1 knock-down yields a higher migratory potential." (PMID 27977010, 2016). "TRAP1 has antiapoptotic functions and plays a role in multidrug resistance in colorectal carcinoma." (PMID 25693800, 2015).
colorectal carcinoma (continued). "However, further work is needed to better clarify the role(s) of TRAP1 in tumorigenesis, as it was also reported that its levels increase during some form of malignant progression, as in prostate cancer or colorectal carcinoma." (PMID 25564869, 2014). "Particularly, in colorectal cancer, over-expression of TRAP1 might encourage tumor cell invasion." (PMID 38098505, 2023). "Thus, the clinical significance of TRAP1 protein network was analyzed in human colorectal cancers." (PMID 28177905, 2017). "The Esposito research group showed that the TNF receptor associated protein (TRAP1), a mitochondrial member of the HSP90 family, which is involved in the protection of oxidative stress, selectively binds eEF1Bγ, and, remarkably, both TRAP1 and eEF1Bγ are co-upregulated in human colorectal cancers." (PMID 27639846, 2016). "This seems to indicate a possible role of TRAP-1 as being responsible for multi-drug resistance in human colorectal cancer: TRAP-1 may give us a potential therapeutic target which has important implications for the efficacy of anticancer agents in cancer therapeutics." (PMID 24970198, 2013). "Upregulated in 60-70% of human colorectal cancers (CRC), TRAP1 regulates the Wnt/β-Catenin pathway and prevents β-Catenin phosphorylation/degradation by modulating the Wnt ligand receptors LRP5 and LRP6, which facilitates stem cell maintenance." (PMID 38098505, 2023). "TRAP1 exerts a role in MDR in cancer cells and is upregulated together with Sorcin in colorectal carcinoma cells; moreover, their interaction is required for Sorcin localization at mitochondria and TRAP1 stability." (PMID 33946271, 2021). "TRAP1 targeting by the mitochondria-directed HSP90 inhibitor Gamitrinib induced apoptosis and inhibited colony formation in BRAF-driven colorectal carcinoma cells, which are known to be poorly responsive to anticancer therapies." (PMID 29621137, 2018). "TRAP1 overexpression creates a resistance to stress stimuli and protects human cancer cells from apoptosis; it is also associated with chemotherapy response and overall survival in ovarian and colorectal cancers, human esophageal squamous cell cancer and non–small cell lung cancer." (PMID 26517089, 2015). "Indeed, TRAP1 modulates the expression of the BRAF oncogene and the two proteins interact in colorectal cancer cells, being frequently co-expressed in human colorectal carcinomas." (PMID 29621137, 2018). "Elevation of TRAP1 protein levels correlates with malignant progression and metastasis in several neoplastic models, including prostate and breast cancer, hepatocellular carcinoma (HCC), and colorectal carcinoma, and with disease recurrence in non-small cell lung cancer." (PMID 28405578, 2017).